FOS (Fos proto-oncogene, AP-1 transcription factor subunit)
Diseases named in the same sentence as FOS in open-access papers (continued):
Sharing a sentence is not in itself a finding about the gene and the disease.
tumor (continued). "By binding to JUN (also JUNB or JUND) or FOS, FOS (also FOSB, FRA1 or FRA2) forms a well-known heterodimeric or homodimeric transcription factor AP-1 which could be oncogenic or tumor-suppressive depending on the cell type." (PMID 38410462, 2024). "In brief, FOS+ S100A2+ Teff subpopulation may play crucial roles in regulating cellular migration, inflammatory responses, and immune reactions within the tumor microenvironment." (PMID 39234254, 2024). "Conversely, FGF7, FOS, and PDGFRA were less expressed in OC tumour samples than in normal tissues." (PMID 39063239, 2024). "In summary, the data highlight the importance of these IRGs in both promoting and preventing tumour progression by indicating a strong correlation between the expression level of genes such as LRP1, PI3, PAEP, FOS, FGF7, and PDGFRA and the degree of tumour immune infiltration in OC." (PMID 39063239, 2024). "Our study demonstrates that cadmium induces MTF-1 binding at FOS/JUN DNA motifs, suggesting a further role in tumor development and one mechanism of how cadmium exposure may transform cells." (PMID 36980293, 2023). "CTCF, FOS, ATF2, and YY1 in H3F3B+ tumor cells were found to regulate angiogenesis." (PMID 37430270, 2023). "• Inhibits transcription in tumor cells by targeting genes like RPB1, MYC, SP1 and FOS." (PMID 36969868, 2023). "Meanwhile, tumor cells in the combination groups showed a higher rate of apoptosis as detected by the TUNEL assay, as well as higher acetylation status, ubiquitination level of HP1γ, suppressed HP1γ level and FOS, JUN and CD40 expression." (PMID 36894562, 2023). "While FOS (c-Fos) and JUN (c-Jun) are known to induce T cell activation, FOS previously has been shown to suppress T cells through PDCD1 and promote tumor progression." (PMID 36305874, 2023). "Mutations of the remaining two FOS genes, FOS Like 1 (FOSL1) and FOS Like 2 (FOSL2), have not been demonstrated in human tumours to date." (PMID 36426824, 2023). "For example, the expression of genes such as JUN, FOS and DUSP1 showed an increasing pattern within the model and turned out to be high in both the tumor and normal samples, suggesting an involvement of these factors in tissue-specific differentiation processes." (PMID 37627150, 2023). "In contrast, non-responding tumours were more memory-like (FOS) and, upregulated GZMK, a typical CD8 TEM marker." (PMID 38030622, 2023). "Furthermore, we also confirmed the regulatory effects of cNFIB on CCND1, MMP1, VEGFA, and FOS expression, the key downstream targets of ERK signaling responsible for tumor proliferation and metastasis." (PMID 35039066, 2022). "Furthermore, the dissociation-related genes FOS, FUN, and HIF1A, were all expressed on the formalin-fixed paraffin-embedded (FFPE) tumor samples." (PMID 36008393, 2022). "Results revealed that tumor volume and weight were significantly enhanced in the presence of oe-KPNA2, whereas KPNA2 and c-FOS expression was upregulated and PRDM1 expression was downregulated accompanied by accelerated cell proliferation and suppressed cell apoptosis." (PMID 33731128, 2021). "CDKN1B, FOS, FOXO1, HDAC1, and RB1 were mainly expressed in the nuclear of tumor cells." (PMID 33748162, 2021). "As a result, several hub DEFs with maximum intramodular connectivity were identified (e.g., SOX4, EGR1, LEF1, FOS, MITF, KLF4, TCF7, and KDM6B), which might involve CD248-mediated tumor-promoting regulation in CAFs." (PMID 34970489, 2021). "Breast cancer is pathologically demarcated by a plethora of abnormal gene profiles and transcripts that drive tumor initiation (MYC, Erb-B2 Receptor tyrosine kinase 2 (ERBB2), tumor progression (FOS, JUNB), proliferation and metastasis (epidermal growth factor receptor (EGRF))." (PMID 34299315, 2021). "FOS, also known as AP-1 subunit, is a major proto-oncogene, EGR1 has been reported to activate the transcription of miR-20b and thereby inhibit the expression of PTEN (a tumor suppressor gene) in breast cancer." (PMID 34151031, 2021).
tumor (continued). "Similarly, in colon cancer, the expression of ODC, MAT2, FOS, and JUN in tumor tissues is higher than that in adjacent normal mucosa to provide polyamines for tumor cell proliferation." (PMID 33292222, 2020). "FOS proto-oncogene (also known as c-FOS) and its paralogue, FOSB proto-oncogene, were differentially expressed in various cancers and play key roles in proliferation, differentiation, migration, and the apoptosis of tumor cells." (PMID 33324350, 2020). "However, both c-FOS and FOSB were shown to be downregulated in NSCLC, suggesting a tumor suppressive role." (PMID 30658436, 2019). "To investigate whether SNHG15 and miR‐338‐3p exert tumor growth promoting function by modulating FOS/RAB14, we checked the effect of FOS and RAB14 on SNHG15‐induced cell proliferation." (PMID 30945457, 2019). "By influencing the tumor microenvironment and the immune system, blocking the expression of COX-2 and the proto-oncogene c-FOS and interfering with the EGF/EGFR pathway, they are able to reduce inflammation, inhibit tumor cell growth, induce apoptosis, and cause autophagy." (PMID 30987191, 2019). "Similar increases in early-response genes including FOS were also reported in 16 patients in whom fine-needle aspirates were taken presurgically and immediately after tumour excision but the time between samples was not stated." (PMID 27036195, 2016). "Interestingly, a recent study showed that the disruption of certain oncosupression transcriptors have been shown to induce both FOS and EGR1 expression in the early stages of tumor development." (PMID 24619124, 2014). "Expression studies obtained by qRT-PCR on day 21 tumor nodules, confirmed a HXR9-based down-regulation of miR-221 and -222 followed by c-FOS restored expression also in vivo, further supporting the option of c-FOS as a direct target of miR-221&222." (PMID 23400877, 2013). "In addition to ESR1/ERα, the top-ranked genes selected by statistical cross-analyses were MET, FOS, SNCG, IGFBP4, and BCL2, which were subsequently validated in a larger set of tumor samples (from 17 control patients and 18 TF patients)." (PMID 18928543, 2008). "Interestingly, we identified the JUN/FOS and ITGB families as key regulators in tumor biology." (PMID 40725477, 2025). "RNA‐seq profiling demonstrated that FOS depletion in LOC388942‐ALK tumor significantly downregulated multiple oncogenic pathways related to cell cycle progression, DNA replication fidelity, and extracellular matrix remodeling, suggesting a pivotal role of FOS in maintaining tumor growth." (PMID 40151836, 2025). "In addition, we found that tumor related genes, such as PTGS2, ADAM17 and FOS, are highly expressed in the ITA infection group, suggesting that ITA may lead to more severe N. farcinica infections." (PMID 40723822, 2025). "We speculate that FOS+ S100A2+ Teff subpopulation promote T-cell infiltration and migration toward tumor regions by increasing S100A2 levels through FOS-mediated transcriptional regulation, thereby inhibiting tumor growth and development." (PMID 39234254, 2024). "During their expansion from this region to other regions, such as clusters 6 and 3 regions, the tumor cells exhibited a more malignant expression pattern, such as high expression levels of malignant markers, such as TNC and TGFBI, as well as active proliferation markers, such as FOS and WEE1." (PMID 39639005, 2024).
tumor (continued). "In addition, abnormal tumor TNF pathways mediated by abnormal expressions of TNF, NF-κB, FOS, JUN, and JUNB were observed, and scATAC-seq results confirmed the presence of abnormal accessibility binding sites for the transcription factors FOS, JUN, and JUNB." (PMID 38770048, 2024). "In addition, activator protein 1 (AP-1, FOS gene) is activated by ROS oxidative stress and is involved in tumor generation and the regulation of vascular endothelial growth factor (VEGF) involved in tumor vasculogenesis." (PMID 37240068, 2023). "However, its copy number profile presented an abundance of CNV (49%) hardly compatible with a benign tumor and no FOS/FOSB gene fusions were detected by RNA sequencing." (PMID 35347251, 2022). "Despite the unknown role of FOS in cancer-induced wasting, FOS heterodimerizes with c-JUN within the AP-1 transcription factor complex, which has been established as a factor required for muscle wasting in AH-130 tumor-bearing rats." (PMID 25539728, 2014). "Moreover, Western blot analysis demonstrated differential protein expression in the NCAM+ALDH1+ tumour, specifically AKTpSer473 but not p-ERK and c-FOS, which have been recently implicated in WT and were strongly expressed in the primary parental WT." (PMID 23239665, 2013). "Consistent with observations in APAs, the phosphorylated forms of FOS and JUN were largely absent in the tumor tissue but remained detectable in both zona glomerulosa and zona fasciculata cells of the non-neoplastic adjacent cortical regions." (PMID 41412035, 2025). "Compared to non-responders, tumor-infiltrating 15.CAR T cells from responders showed repression of SWI/SNF epigenetic regulators and upregulation of FOS and JUN family members as well as genes related to type I interferon signaling." (PMID 38645165, 2024). "Given the finding that c-FOS also transactivates FOSL1 expression and functions as an oncogene to promote tumor cell growth, it is not surprising that overexpression of c-FOS promotes EMT and accelerates tumor development and progression." (PMID 37353480, 2023). "Tumor cells with fused genes showed overexpression of FOSB, FOS, and JUN, while tumor cells without fused genes overexpressed CXCR6 and DUSP4." (PMID 37736898, 2023). "Furthermore, XFZYD decreased the expression of c-FOS and increased the mRNA levels of rpr, hid, and grim in the RasV12/lgl−/− background, indicating that XFZYD may hinder tumour cell invasion by suppressing JNK/AP-1 signalling and promoting tumour cell apoptosis by activating caspase signalling." (PMID 35903326, 2022). "The relative expressions of EGR1, FOS, and FOSB mRNA were 0.493±0.558-, 0.494±0.476-, and 0.500±0.551-fold downregulated in 20 tumor tissues versus adjacent nontumor tissues, respectively." (PMID 30228980, 2018). "However, it is to be noted that in both cell lines and tumours, data showed a trend that was not statistically significant given the low number of samples analysed and the huge heterogeneity of expression shown by HMGA1, FOS and MYC in tumors." (PMID 22363436, 2012).
cancer (351 papers, 2008 to 2026). A tumor composed of atypical neoplastic, often pleomorphic cells that invade other tissues. "FOS, a proto-oncogene responsible for encoding a nuclear DNA binding protein, plays a pivotal role in several types of cancer directly impacting signal transduction, cell differentiation, and proliferation." (PMID 40862714, 2025). "Mechanistically, SF3A3 promotes the alternative splicing of c‐FOS, a proto‐oncogene implicated in cancer progression, leading to increased full‐length c‐FOS expression and upregulation of the anti‐apoptotic Bcl2/Bax ratio." (PMID 40598817, 2025). "The volcano plot of DEGs between 11 wart and 7 cancer samples of patients with EV shows differential expression of cancer-associated genes, such as FOS, JUND, PCNA, CHEK1, and CDKN2A." (PMID 36602881, 2023). "Aberrant expression and activation of FOS proteins is driven by dysregulation of key cancer-associated signalling pathways, most notably the ERK MAPK pathway." (PMID 36077499, 2022). "FOS is a proto-oncogene encoding a transcription factor overexpressed in a variety of cancers, including thyroid, bladder and pancreatic." (PMID 31749682, 2019). "Some reports have implicated that c-FOS (a member of the transcription factor AP-1 component) plays an important role in the tumorigenesis of several human cancers." (PMID 27494869, 2016). "The transcription factor (TF) FOS, a key component of the AP-1 complex, was linked to tumor progression and therapy resistance in various cancers, but its precise mechanisms remained unclear, and its role in lung adenocarcinoma (LUAD) was unknown." (PMID 40936936, 2025). "The results indicated that these TFs—HIF1A, JUN, LEF1, and FOS—were negatively correlated with four glycolysis-associated lncRNAs across the five cancer types, suggesting that the low expression of these lncRNA signatures was accompanied by glycolytic signaling and oncogenic TF activation." (PMID 33627136, 2021). "For example, JUN and FOS are associated with cancer drug resistance and metastatic progression." (PMID 31623682, 2019). "The single-cell sequencing bioinformatics analysis in this study found that CXCL8 (IL-8) expression was associated with c-FOS, which was consistent with previous studies that indicated that IL-8 could induce NETs, elevating the cascade effect exerted by NETs on cancer." (PMID 40148973, 2025). "The results demonstrate that ITGB1 and its target genes FOS/JUN were commonly expressed in all four cancer types, indicating their potential as pan-cancer therapeutic targets." (PMID 40725477, 2025). "The FOSB and FOS genes, part of the AP-1 transcription factor complex, regulate gene expression in response to various stimuli, including those related to cancer development." (PMID 40361912, 2025). "FOS gene has been recognized as an oncogene in NB; moreover, it can be modulated in cancer cells treated with anti-cancer drugs." (PMID 40089488, 2025). "Fos proto-oncogene, AP-1 transcription factor subunit (FOS) gene has been recognized as an oncogene in human malignant tumors, including NB; moreover, it can be modulated in cancer cells treated with anti-cancer drugs." (PMID 40089488, 2025). "Recently, it was shown that components of the AP-1 transcription factor (FOS, FOSB, JUN), EGR1, and NR4A1 behave as a conserved co-regulated group of genes whose expression is associated with ZFP36 in cancer cells." (PMID 39026155, 2024). "Dysregulation of the FOS and JUN family is associated with cancer therapy resistance and poor patient survival." (PMID 38385626, 2024). "Our recent study showed that FOS inhibitor T‐5224 suppressed the growth of TERT mutant cancer cells through downregulating GABPB and the transcription of TERT in the presence of TERT promoter mutation." (PMID 38769666, 2024).
cancer (continued). "Conversely, the AhR complex inhibits ESR signaling in the presence of estrogen that would otherwise normally transcribe genes such as FOS, CTSD, HSP27, and TFF1, which are over-expressed and/or mutated in various cancers." (PMID 37027342, 2023). "Together, these clinical findings are consistent with our results in mice, suggesting an opportunity to use murine systems to further explore how GATA3 regulates FRA1 and c-FOS to control human breast biology as well as cancer development and progression." (PMID 37353480, 2023). "The FOS protein has been widely reported in several cancers and inflammatory diseases as a regulator of cell proliferation, differentiation, and transformation." (PMID 37138755, 2023). "The transcription factor FOS is essential for normal cell proliferation and differentiation, and its elevated levels are often observed in various types of cancer, classifying FOS as a proto-oncogene." (PMID 38139251, 2023). "Considering our data, FOS would possibly be a potential druggable gene to rewire the metabolic status of dedifferentiated hepatocytes in cancer." (PMID 37907970, 2023). "Our findings provide novel insights into the role of NQO1/c-FOS/CKS1 signaling in cancer, highlighting an innovative avenue for anticancer therapeutic strategies targeting this pathway." (PMID 36793872, 2023). "For instance, proliferation- and cell survival-promoting TFs, such as MYC, Jun-, FOS- and E2F family TFs, were found to have significantly increased activity across the three cancer types." (PMID 37843125, 2023). "Previous reports using normal epithelial tissues and carcinomas revealed that warm enzymatic dissociation (i.e., at 37 °C) invoked a distinct ‘Warm Dissociation Signature’ enriched in FOS, FOSB, and JUN." (PMID 37254069, 2023). "Leakage from cancer cells raises the expression of the AP1 component c-FOS, which raises the expression of PD-1." (PMID 36363529, 2022). "In some cancers, co-expression of IEGs, such as FOS, JUN, and EGR1, was positively correlated with poor survival." (PMID 36505794, 2022). "A large number of genes are affected by the FOS proteins and the AP-1 are well-known in the fields of cancer research, inflammation, immunity, and bone development." (PMID 35592695, 2022). "Most genes related to signal transduction in the cytoplasm were inactivated in the pathway of the Molecular Mechanism of Cancer; however, the gene expression of NF-κB, c-FOS, c-JUN, MDM2, AURORA-A, BBC3, BIM, and p21CIP1 was significantly increased." (PMID 35328637, 2022). "We used nude mouse xenograft models to confirm a role for the CRART16/miR-122-5p/FOS axis in regulating cancer cell growth and angiogenesis." (PMID 35537818, 2022). "FOS is a proto-oncogene with an essential role in many kinds of cellular functions and is overexpressed in various cancers." (PMID 35537818, 2022). "LY6E, MUC1, and FOS play important roles in immune escape and suppressive immune microenvironment in various types of cancers." (PMID 33144684, 2021). "We were particularly interested in studying those genes that are associated with cancer progression, TME signals, and poor prognosis such as LY6E, NAPSA, MUC1, ELF3, and FOS." (PMID 33144684, 2021). "We have proven that TFII‐I was a key partner for circARHGAP35 protein to exert its oncogenic functions, thereby demonstrating the need for the circARHGAP35 protein by cancer cell lines to establish and maintain an oncogenic transcriptome (e.g., FOS)." (PMID 34258149, 2021). "In cancer cells as well, the tumor cell leakage enhances the expression of c-FOS subunit of AP-1, which in turn, enhances the PD-1 expression." (PMID 35002724, 2021).